SLC66A2 (solute carrier family 66 member 2)
Synonyms: PQLC1; FLJ22378
Tractability: Antibody: UniProt predicts a signal peptide or a membrane-spanning region. PROTAC: ubiquitination databases record sites on it.
Gene: Protein-coding gene on chromosome 18 (79,902,420 to 79,951,676, reverse strand). Ensembl gene ENSG00000122490.
Subcellular location: Membrane
Subcellular location (Human Protein Atlas): Nucleoplasm
Gene Ontology:
Molecular function: protein binding
Biological process: phospholipid translocation; retrograde transport, endosome to Golgi
Cellular component: endosome membrane; trans-Golgi network membrane; cytosol; membrane
Genetic constraint (gnomAD): Loss-of-function variants: 26 observed, 28.58 expected, observed/expected ratio (o/e) 0.91, 90% interval 0.67 to 1.26. The upper end of that interval is the gene's LOEUF score, 1.26, which puts it in group 5 of 6, group 1 being the genes least tolerant of losing a copy. Missense variants: 396 observed, 384.73 expected, observed/expected ratio (o/e) 1.03, 90% interval 0.95 to 1.12. Synonymous variants: 193 observed, 171.64 expected, observed/expected ratio (o/e) 1.12, 90% interval 1 to 1.27.
Homologues: Orthologues: chimpanzee SLC66A2 (99% identical), macaque SLC66A2 (99% identical), rat Slc66a2 (89% identical), mouse Slc66a2 (89% identical), guinea pig SLC66A2 (86% identical), tropical clawed frog slc66a2 (75% identical), rabbit SLC66A2 (70% identical), pig SLC66A2 (66% identical), zebrafish SLC66A2 (65% identical), dog SLC66A2 (61% identical), Drosophila melanogaster CG13784 (48% identical), Caenorhabditis elegans T19A6.1 (40% identical).
Diseases named in the same sentence as SLC66A2 in open-access papers:
SLC66A2 is named in the same sentence as 2 diseases in open-access papers, as found by Europe PMC text mining. Sharing a sentence is not in itself a finding about the gene and the disease.
SLC66A2 shares sentences with these, for which no sentence is quoted: cancer (1 paper); myopia (1).